SLC35F2 (solute carrier family 35 member F2)
Diseases named in the same sentence as SLC35F2 in open-access papers (continued):
Sharing a sentence is not in itself a finding about the gene and the disease.
cancer (continued). "We showed that one mutation in 3′UTR might increase the protein expression of SLC35F2, providing indications that UTR mutations might be involved in gene regulation and, subsequently, in cancer progression." (PMID 33418944, 2021). "We believe that understanding the physiological role of SLC35F2 in BC could provide new therapeutic opportunities with the anti-cancer drug YM155 being beneficial in patients with high levels of SLC35F2." (PMID 33418944, 2021). "For future application of YM155 and its analogs as both stemotoxic compounds and anti-cancer drugs, it is important to determine the structure of SLC35F2 to facilitate the design of more potent YM155 analogs with increased uptake, and hence enhanced stemotoxic activity." (PMID 31157201, 2019). "In this study, we detected the SLC35F2 expression in 60 pairs of PCa patients' tumor tissues and adjacent tissues and found that it was remarkably upregulated in tumors and positively related to poor prognosis, indicating that SLC35F2 might be a cancer-promoting gene in PCa." (PMID 35669242, 2022). "Therefore, understanding the molecular mechanism of SLC35F2 in the progression of cancer might provide new therapeutic opportunities against BC." (PMID 33418944, 2021). "Therefore, this study intends to observe the effects of downregulation of SLC35F2 on the sensitivity to chemotherapy in PCa in vivo and in vitro, so as to lay a theoretical foundation for the clinical enhancement of the chemotherapy sensitivity of PCa and other malignant tumors." (PMID 35669242, 2022). "YM155-resistant cancer cells in particular exhibited elevated expression of USP32 and low expression of SLC35F2." (PMID 34815782, 2021). "Herein, we explicitly refer to the SLC35F2 cargo YM155, which is currently tested in clinical trials for treatments of different cancer types." (PMID 33418944, 2021). "To corroborate the negative correlation between USP32 and SLC35F2, we estimated the expression of these two proteins in several cancers." (PMID 34815782, 2021). "Due to the fact that the increase in SLC35F2 protein directly affects YM155 uptake, we were interested in the putative DUBs upon knockout that resulted in increased SLC35F2 protein, as part of our effort to identify new cancer targets." (PMID 34815782, 2021). "The functional role and molecular mechanisms of SLC35F2 in cancer development have not yet been comprehensively investigated." (PMID 33418944, 2021). "In addition, the functional role of SLC35F2 in several diseases and cancer types has not been analysed intensively so far." (PMID 33418944, 2021). "Because knockout of SLC35F2 in hESCs completely prevented hESC cell death by YM155 and its analogs, we speculate that hydrogen bonding interactions between YM155 and SLC35F2 may be critical for YM155 uptake, and consequentially for cytotoxic activity against both cancer cells and hPSCs." (PMID 31157201, 2019). "The high score for USP32 mRNA level in any given cancer cell line was inversely proportional to the SLC35F2 mRNA, which suggests a significant negative correlation between USP32 and SLC35F2 with a r value of -0.1789." (PMID 34815782, 2021). "However, cellular ABCB1 and SLC35F2 levels did not indicate YM155 sensitivity in YM155-naïve cells, as indicated by drug response data derived from the Cancer Therapeutics Response Portal (CTRP) and the Genomics of Drug Sensitivity in Cancer (GDSC) databases." (PMID 32357518, 2020).
tumor (10 papers, 2013 to 2025). "We identified various tumour-associated genes, including SLC35F2, to be frequently mutated in our patient samples." (PMID 33418944, 2021). "From the DNA sequencing analysis of matched non-muscle-invasive bladder cancer (NMIBC) and muscle-invasive bladder cancer (MIBC) samples from eight patients, we identified the tumour-associated gene SLC35F2 to be mutated in the 5′ and 3′ untranslated region (UTR)." (PMID 33418944, 2021). "USP32 participates in tumor growth and resistance to therapy via the deubiquitination modification of tagged substrates, such as Rap1b and SLC35F2, suggesting that USP32 is a potential therapeutic target." (PMID 40136417, 2025). "In this group of tumour cells, we also detected some cells with an atypically strong and selective staining of SLC35F2 around the nucleus in MIBC." (PMID 33418944, 2021). "USP32 expression was decreased in USP32KO groups and SLC35F2 expression was upregulated in these tumor tissues." (PMID 34815782, 2021). "In line with the observation from the expression analysis of SLC35F2 in tumour samples, we investigated the influence of SLC35F2 knockdown on BCa cells T24 and Cal29 by transfection with siRNA against SLC35F2." (PMID 33418944, 2021). "In this study, we identified frequent mutations in the 5′ and 3′ untranslated region (UTR) of various tumour-associated genes, including SLC35F2, from whole-exome and UTR sequencing and focused on the investigation of the functional role of SLC35F2 in BC." (PMID 33418944, 2021). "To further confirm the correlation, we analyzed USP32 and SLC35F2 expression in different human tumor tissues." (PMID 34815782, 2021). "Altogether, the depletion of USP32 enhances YM155-mediated sensitivity by stabilizing SLC35F2 protein, which hampers tumor progression." (PMID 34815782, 2021). "Furthermore, in immunohistochemical staining, we observed a strong intensity of SLC35F2 in single tumour cells and in the border cells of solid tumour areas with an atypical accumulation around the nucleus, especially in the MIBC." (PMID 33418944, 2021). "In PTC, SLC35F2 expedites the proliferation and migration of tumor cells by targeting TGFBR1." (PMID 34335744, 2021). "As mentioned, SLC35F2 acts as an oncogene in various tumour entities." (PMID 33418944, 2021). "SLC35F2 gene expression is higher in NSCLC tissue than in normal lung tissues near the tumor." (PMID 23879892, 2013). "This suggests that SLC35F2 might be highly expressed in aggressive and invasive tumour cells." (PMID 33418944, 2021). "Furthermore, we analysed the protein expression of SLC35F2 in corresponding FFPE tumour tissues." (PMID 33418944, 2021). "Here, we show an increased staining (moderate to strong) of SLC35F2 in single tumour cells and in the cells of the border of solid tumour areas in MIBC compared with matched NMIBC samples, suggesting that these cells might be responsible for the invasiveness and aggressiveness of BC." (PMID 33418944, 2021). "Furthermore, we do not observe the heterogeneity of SLC35F2 expression associated with the HCC clinical tumor samples, indicating that SLC35F2 is unlikely to be the sole factor defining the heterogeneous sensitivity of HCC cells to YM155." (PMID 25714025, 2015). "The Department of Thoracic Surgery in Peking University People's Hospital reported that the expression of the SLC35F2 protein is obviously higher in non-small-cell lung carcinoma (NSCLC) tissue than in normal tissues near the tumor, indicating that SLC35F2 might be a potential oncogene." (PMID 23879892, 2013). "YM155 is a substrate of human and mouse SLC35F2, and SLC35F2 is a major determinant of YM155 antitumour efficacy in xenografted models, comparing the effects of YM155 on tumour growth between wild-type and SLC35F2 KO SW480 cells." (PMID 35631480, 2022).
tumor (continued). "In addition, high USP32 expression plays a crucial role in tumor growth, metastasis, immune infiltrates, and chemoresistance via the deubiquitination of various substrate proteins, such as Smad2, SHMT2, FDFT1, Rab7, SLC35F2, and BAG3." (PMID 40136417, 2025). "Nevertheless, we did not detect an increased average staining in the tumour with the 3′UTR mutation compared with other NMIBC, which suggests that this 3’UTR mutation may play a minor role in the biology of SLC35F2." (PMID 33418944, 2021).
SLC35F2 also shares sentences with these, for which no sentence is quoted: bipolar disorder (1 paper); chondrosarcoma (1); Immunodeficiency (1); schizophrenia (1); severe combined immunodeficiency (1); thyroid cancer (1); unipolar depression (1).